GSDME (gasdermin E)
Diseases named in the same sentence as GSDME in open-access papers (continued):
Sharing a sentence is not in itself a finding about the gene and the disease.
colon cancer (continued). "Taken together, these data suggest that GSDME is essential for lobaplatin-induced pyroptosis in colon cancer cells and that knocking out GSDME switches lobaplatin-induced cell death from pyroptosis to apoptosis." (PMID 30804337, 2019). "Taken together, these results indicated that GSDME is cleaved in lobaplatin-induced pyroptosis in colon cancer cells." (PMID 30804337, 2019). "Therefore, in colon cancer cells, GSDME mediates lobaplatin-induced pyroptosis downstream of the ROS/JNK/Bax-mitochondrial apoptotic pathway and caspase-3/-9 activation." (PMID 30804337, 2019). "Thus, we aimed to investigate whether GSDME is essential for lobaplatin-induced pyroptosis in colon cancer cells." (PMID 30804337, 2019). "They confirmed synergism of cytokines TNF-α and IFN-γ was capable of inducing PANoptosis of colon cancer cells through activation of GSDMD, GSDME, caspase-8, caspase-3, caspase-7 and MLKL, thereby suppressing tumor growth." (PMID 36505474, 2022). "In summary, these data suggest that CVB3 infection of colon cancer cells increases ROS levels, which drives CVB3-induced pyroptosis of colon cancer cell lines by activating the casp-3/GSDME pathway." (PMID 36551691, 2022). "Another study reported that the knockdown of GSDME shifted loplatin-induced cell death from cell scorching to apoptosis, but did not affect the growth and tumor formation of colon cancer cells treated with loplatin." (PMID 35419279, 2022). "This demonstrates that CVB3 induces pyroptosis of colon cancer cell lines through the casp-3/GSDME pathway and not the GSDMD pathway." (PMID 36551691, 2022). "Another study reported that knocking out GSDME switches lobaplatin-induced cell death from pyroptosis to apoptosis but does not affect the growth and tumor formation of colon cancer cells treated with lobaplatin." (PMID 34305590, 2021). "DFNA5 (GSDME) has been reported to induce high methylation in the putative gene promoter and is downregulated in many tumor cell lines, including breast, gastric, and colon cancer cell lines." (PMID 32437063, 2020). "Taken together, these results suggest that GSDME knockout switches lobaplatin-induced pyroptosis to apoptosis but does not affect tumour formation in colon cancer cells treated with lobaplatin." (PMID 30804337, 2019). "In summary, these data indicated that GSDME rather than GSDMD is cleaved in lobaplatin-induced pyroptosis in colon cancer cells and that the cleavage of GSDME is due to caspase-3 activation." (PMID 30804337, 2019). "However, our study indicated that knocking out GSDME switches lobaplatin-induced cell death from pyroptosis to apoptosis but does not affect the growth and tumour formation of colon cancer cells treated with lobaplatin." (PMID 30804337, 2019). "Similarly, the evidence of ZEB1/GSDME involvement in the regulation of EMT markers upon ETAR activation in breast and colon cancer, suggested that this novel EMT-related nuclear function of GSDME may be common to various tumor histotypes, in addition to HG-SOC." (PMID 41545335, 2026). "GSDME, rather than GSDMD, was demonstrated to be cleaved in lobaplatin-induced pyroptosis in colon cancer cells due to caspase-3 activation, which clarified the mechanism of lobaplatin eradicating neoplastic cells." (PMID 36505474, 2022).
esophageal squamous cell carcinoma (23 papers, 2020 to 2025). Esophageal squamous cell carcinoma (ESCC) is a type of esophageal carcinoma (EC) that can affect any part of the esophagus, but is usually located in the upper or middle third. "In addition, the expression of pyroptosis related gene GSDME in esophageal squamous cell carcinoma was higher than that in normal cells, while the high expression of GSDME was associated with pyroptosis." (PMID 37302999, 2023). "In esophageal squamous cell carcinoma, GSDME expression is notably elevated in cancer tissues compared to that in normal tissues." (PMID 38066523, 2023). "GSDME protein levels were increased in esophageal squamous cell carcinoma (ESCC) and positively corresponded to a favorable prognosis." (PMID 36920176, 2023). "The Plk1 kinase inhibitor BI 2536 was previously confirmed to induce pyroptosis in the caspase-3/GSDME pathway in esophageal squamous cell carcinoma." (PMID 36016611, 2022). "DDP was reported to increase the chemosensitivity of esophageal squamous cell carcinoma both in vivo and in vitro by inducing bax/caspase-3/GSDME-dependent pyroptosis." (PMID 32209729, 2020). "As such, GSDME emerges as a valuable prognostic marker in esophageal squamous cell carcinoma." (PMID 38066523, 2023). "In esophageal squamous cell carcinoma (ESCC) tissues, the expression level of GSDME has been reported to be higher than in normal esophageal tissues." (PMID 34553845, 2022). "GSDME is upregulation in the oesophageal squamous cell carcinoma (ESCC) compared to the normal tissue." (PMID 35896522, 2022). "In the context of esophageal squamous cell carcinoma (ESCC), photodynamic therapy (PDT) has been shown to directly inhibit PKM2, thereby activating the PKM2/caspase-8/caspase-3/GSDME axis." (PMID 41169372, 2025). "Also, while GSDME expression is higher in esophageal squamous cell carcinoma (ESCC) compared to the normal tissue, its overexpression is associated with better prognosis." (PMID 40691738, 2025). "Finally, gefitinib 53 acts as a PLK1 kinase inhibitor, and it induces pyroptosis in esophageal squamous cell carcinoma (ESCC) and various other cancer types by triggering caspase-3, GSDME, and Bax activation." (PMID 39316325, 2025). "By inhibiting the last enzyme involved in glycolysis, pyruvate kinase (PMK-2), and consequently activating caspase-8 and caspase-9, ultimately leading to the release of gasdermin E (GSDME), PDT can induce pyroptosis of esophageal squamous cell carcinoma cells." (PMID 38201494, 2023). "Inhibition of PLK1 by BI2536 treatment in esophageal squamous cell carcinoma (ESCC) induced pyroptosis both in vitro and in vivo through the BAX/caspase-3/GSDME pathway and boosted the sensitivity to cisplatin." (PMID 35719948, 2022). "The expression level of GSDME was significantly increased in esophageal squamous cell carcinoma (ESCC) tissues than in normal esophageal tissues and was significantly correlated with a better prognosis in patients with ESCC." (PMID 35659304, 2022). "In esophageal squamous cell carcinoma (ESCC), BI2536, an inhibitor of polo-like kinase 1(PLK1), was found to activate caspase-3 and BAX in combination with cisplatin, resulting in GSDME disruption and increased DNA damage." (PMID 35359956, 2022).
hepatocellular carcinoma (23 papers, 2018 to 2025). A malignant tumor that arises from hepatocytes. "Our work developed a comprehensive blueprint for the underlying mechanism through which GSDME accelerates the malignant progression of hepatocellular carcinoma and provided novel insights into the development of therapeutic targets as well as potential biomarkers for patients with LIHC." (PMID 37149620, 2023). "The data in this study showed that Tc3 emerged as a promising lead compound, exhibiting potent induction of GSDME-mediated pyroptosis both in vitro and in vivo in hepatic carcinoma via activated PERK and the ER stress." (PMID 39816682, 2025). "Although GSDME is often low-expressed in various tumor cells, the mRNA and protein level of GSDME remain normal in hepatic carcinoma cells according to our work, which is crucial for the anti-tumor effect of Tc3." (PMID 39816682, 2025). "In this work, we attempt to activate GSDME and induce pyroptosis to inhibit hepatic carcinoma growth by Tc3." (PMID 39816682, 2025). "Another study showed that miltirone induces hepatocellular carcinoma cell death by GSDME-dependent pyroptosis." (PMID 37658132, 2023). "In this study, by using morphological observation, fluorescence double staining, LDH release and immunoblot detection, we confirmed for the first time that HGS-ETR1/2 can induce GSDME-mediated pyroptosis in hepatocellular carcinoma cells." (PMID 38049405, 2023). "We found that HGS-ETR1/2 can not only induce apoptosis of cells but also induce GSDME-mediated pyroptosis in hepatoma cells." (PMID 38049405, 2023). "The poor prognosis of patients with hepatocellular carcinoma as well as head and neck squamous cell carcinomas have been proven to be highly correlated with the high expression of GSDME." (PMID 35462927, 2022). "GSDME plays a key role in the pyroptosis process, and the GSDME gene is silenced in many human cancer cells including gastric, colorectal, hepatocellular carcinoma, and breast cells." (PMID 34305590, 2021). "GSDME suppressed the proliferation of hepatocellular carcinoma (HCC) cells by inducing cell cycle arrest." (PMID 33634141, 2021). "It is hypothesized that the reactive oxygen species (ROS) may be induced by Tc3, further stimulating the ER and triggering GSDME-mediated pyroptosis in hepatic carcinoma cells." (PMID 39816682, 2025). "Here, we further knocked down or over-expressed GSDME in hepatic carcinoma cells to verify whether Tc3 could induce a change in the cell death mechanism." (PMID 39816682, 2025). "However, research on potent GSDME agonists and pyroptosis inducers for hepatic carcinoma is limited." (PMID 39816682, 2025). "As a primary responder of Tc3, GSDME was relatively highly expressed in hepatic carcinoma cells, and the full-length GSDME could be up-regulated by Tc3, ensuring a better effect of Tc3 on hepatocarcinoma." (PMID 39816682, 2025). "GSDME was up-regulated in hepatic carcinoma cells by Tc3, indicating that Tc3 may overcome the restrictions of GSDME expression at the protein level." (PMID 39816682, 2025). "In addition to HLCZ01 cells, we also detected HGS-ETR1/2 induced GSDME cleavage and cell lysis death in HepG2 and Huh7 hepatoma cells." (PMID 38049405, 2023). "Hepatocellular carcinoma (HCC) displays an aberrant GSDME overexpression pattern, which promotes immune suppression and resistance to anti-PD-1 therapy through pyroptosis-independent mechanisms." (PMID 40568597, 2025). "Similarly, our data demonstrated that Tc3 could activate the TIME in mice and increase tumor-infiltrating lymphocytes, which is worthy of consideration as a potent pyroptosis inducer and GSDME activator for inhibiting hepatic carcinoma." (PMID 39816682, 2025). "GSDME knockdown could markedly suppress the growth of hepatocellular carcinoma." (PMID 39607202, 2024). "In hepatocellular carcinoma (HCC), overexpression of GSDME in HepG2 cells inhibits cell proliferation by increasing apoptosis and cell cycle arrest." (PMID 37125240, 2023).
hepatocellular carcinoma (continued). "Further detection of GSDM proteins expression in hepatoma cells showed that HGS-ETR1/2 can induce the activation of GSDME, but not GSDMD, by cleavage." (PMID 38049405, 2023). "Although CBD induces apoptosis in a broad range of cancers, it targets hepatocellular carcinoma (HCC) cells by inducing pyroptosis, as indicated by a balloon-like morphology; LDH release; and cleavage of caspase-3, PARP, and GSDME." (PMID 36361743, 2022).
colitis (14 papers, 2020 to 2025). Inflammation of the colon. "How to inhibit GSDME‐mediated pyroptosis is one of a promising target for colitis‐associated human CRC therapeutic strategies." (PMID 37125240, 2023). "In our previous study, we found that GSDME deficiency protected mice from DSS-induced colitis." (PMID 40103680, 2025). "To investigate the role of GSDME in colitis development, we established a DSS-induced colitis model with Gsdme−/− mice and WT littermate controls and found that Gsdme−/− mice were resistant to DSS-induced colitis, exhibiting less weight loss and disease activity index than WT controls." (PMID 33160389, 2020). "We show that GSDME-mediated epithelial pyroptosis contributes to the development of DSS-induced colitis by promoting intestinal inflammation and disrupting the intestinal epithelial barrier." (PMID 40103680, 2025). "Our FITC-dextran permeability experiment indicates that GSDME deficiency is helpful for maintaining the integrity of the IEC barrier, which resulted in the resistance of GSDME-KO mice to experimental colitis." (PMID 40103680, 2025). "GSDME deficiency effectively reduces HMGB1 release from colonic tissues, alleviating inflammation in a mouse model of DSS-induced colitis." (PMID 35677444, 2022). "In this study, we found that GSDME deficiency in the nonhematopoietic cells significantly alleviated DSS-induced colitis." (PMID 40103680, 2025). "Here, we explored the functional relevance of epithelial GSDME in DSS-induced colitis in mice and investigated whether GSDME-mediated pyroptosis participates in the development of DSS-induced colitis." (PMID 40103680, 2025). "Moreover, GSDME deficiency in mice restricted DSS-induced IEC pyroptosis and maintained the integrity of the intestinal epithelial barrier, leading to experimental colitis resistance." (PMID 40103680, 2025). "GSDME-mediated pyroptosis reportedly promotes intestinal inflammation progression in CD by releasing pro-inflammatory cytokines, whereas its knockdown in IECs can protect from trinitro-benzene-sulfonic acid-induced colitis in mice." (PMID 39706833, 2024). "In colitis‐associated CRC, released HMGB1 could trigger GSDME‐mediated pyroptosis to promote tumor cells proliferation by ERK1/2 pathway." (PMID 37125240, 2023). "Furthermore, the colons of GSDME-deficient mice contained fewer infiltrating MPO+ neutrophils and F4/80+ macrophages in DSS-induced colitis, indicating that GSDME contributes to DSS-induced colitis through recruiting inflammatory immune cells and initiating inflammatory responses." (PMID 40103680, 2025). "Collectively, these data indicate that GSDME-mediated and Caspase-3-dependent pyroptosis participates in DSS-induced colonic inflammation." (PMID 40103680, 2025). "Therefore, we speculated that GSDME may promote DSS-induced colitis through mediating pyroptosis." (PMID 40103680, 2025). "To investigate whether GSDME affects intestinal barrier disruption in the DSS-induced colitis model, we determined FITC-dextran in the serum of GSDME-KO mice and WT control littermates 7 days after DSS treatment." (PMID 40103680, 2025). "Collectively, these data implicate that the lack of GSDME in the epithelial or stromal cells protected the mice against DSS-induced colitis." (PMID 40103680, 2025). "We observed increased GSDMC mRNA expression in IBD patients and cleavage of GSDMC was upregulated in experimental colitis mice, suggesting that GSDMC may be involved in IBD, similarly to GSDME and GSDMD." (PMID 37740137, 2023). "Furthermore, deletion of GSDME effectively reduces HMGB1 expression and release in colonic tissue models and alleviates inflammation in mouse models of DSS-induced colitis." (PMID 35677444, 2022). "In this study, we found that genetic deletion of GSDME, an important executor protein of pyroptosis, could effectively decrease HMGB1 expression and release from colonic tissues in a DSS-induced colitis model." (PMID 33160389, 2020).
neuroblastoma (13 papers, 2018 to 2026). Neuroblastoma (NB) is the most common solid, extracranial childhood tumor. "In particular, topotecan, etoposide, cisplatin, and CPT-11 have been observed to trigger pyroptosis in SH-SY5Y neuroblastoma cells and MeWo skin melanoma cells, both of which exhibit high levels of gasdermin E (GSDM-E) expression." (PMID 40149884, 2025). "Previous studies have reported that chemical drugs can induce neuroblastoma cell SH-SY5Y to develop cell pyroptosis, which is associated with high-level endogenous GSDME expression." (PMID 38177154, 2024). "We measured the mRNA levels of the gasdermin family genes (GSDMA, GSDMB, GSDMC, GSDMD and GSDME) in all five wild-type NB cell lines to understand the genes activated in neuroblastoma." (PMID 38893185, 2024). "Collectively, these data suggest that CASP2 is essential for HSV‐2‐induced GSDME‐dependent pyroptosis in human SH‐SY5Y neuroblastoma cells." (PMID 37646198, 2023). "Overall, the results indicate that the IRE1α‐JNK pathway is the major driver of the GSDME‐dependent pyroptosis in productively HSV‐2‐infected neuroblastoma cells." (PMID 37646198, 2023). "Interestingly, recent evidence demonstrates that the neuroblastoma SH-SY5Y cell line expresses high levels of GSDME." (PMID 38177154, 2024). "Furthermore, an analysis of the Cancer Genome Atlas (TCGA) cohort unveiled that neuroblastoma exhibits significantly higher levels of GSDME when compared with 31 other types of tumor tissues, second only to brain tumors." (PMID 38177154, 2024). "In the SH‐SY5Y neuroblastoma cells system, CRISPR/Cas9‐mediated genome editing of both CASP3 and CASP7 was required to abolish GSDME cleavage (Fig EV1L and M)." (PMID 37646198, 2023). "Indeed, cleavage of GSDME by caspase-3 has been observed only in certain GSDME-expressing cancer cells, such as SH-SY5Y neuroblastoma cells and MeWo cells." (PMID 33665167, 2020).
viral infection (13 papers, 2017 to 2025). "These experiments extend the relevance of mtRNA-triggered inflammation to viral infection and implicate GSDME as a parallel mediator of this response." (PMID 41550948, 2025). "This highlights the necessity of investigating the potential roles of GSDMs, especially GSDME, in the induction of inflammatory responses and subsequent pathological injury by viral infections." (PMID 40503916, 2025). "We demonstrate that during virus infection caspase-3 cleaves and activates gasdermin E (GSDME), another key executioner of pyroptosis." (PMID 38932190, 2024). "Accordingly, GSDME knockout cells show a significant decrease in lytic cell death upon virus infection." (PMID 38932190, 2024). "We also found that GSDME is proteolytically activated by caspase-3 in the context of viral infection." (PMID 38932190, 2024). "Caspase-3 was reported to specifically cleave gasdermin E (GSDME), leading to chemotherapy drug-induced normal-tissue damage or viral infection-mediated secondary necrosis 18,19, revealing that GSDME also has pyroptotic potential." (PMID 38250606, 2024). "Generally, caspase‐3 is reported to specifically cleave GSDME, leading to GSDME‐mediated pyroptotic cell death when viral infection or chemotherapy drugs are used." (PMID 34459122, 2021). "However, DMF pretreatment significantly inhibited both GSDME cleavage and TBK1 phosphorylation, highlighting the role of GSDME cleavage in TBK1 activation during viral infection." (PMID 41550948, 2025). "Moreover, several studies have demonstrated that GSDME-mediated pyroptosis can occur in certain circumstances of viral infection (35, –, 40)." (PMID 40503916, 2025). "Similarly, DMF pretreatment in A549 cells and PM cells infected with VSV reduced cytosolic mtRNA levels, confirming GSDME-mediated mitochondrial pore formation during viral infection." (PMID 41550948, 2025). "Therefore, GSDME possesses the ability to regulate apoptosis and pyroptosis in response to caspase 3 activators, including chemotherapeutic drugs, tumor necrosis factor, and viral infection." (PMID 38388468, 2024). "Therefore, to further explore the role of gasdermins in the context of viral infection, the virus-induced lytic cell death and IL-1β release were assessed in cells silenced for GSDMD and GSDME expression using siRNA." (PMID 37680489, 2023). "At the same time, we found that CT26 and CMT93 VT also exhibited natural hyperactivation of GSDMD, GSDME, and p-MLKL, because they were constructed by cas9-expressing lentiviral vector, they could induce natural hyperactivation of GSDMD, GSDME, and p-MLKL through viral infection." (PMID 38740747, 2024).